CD5L (CD5 molecule like)
Diseases named in the same sentence as CD5L in open-access papers (continued):
Sharing a sentence is not in itself a finding about the gene and the disease.
tumor (continued). "Analysis of the downstream pathways demonstrated prominent activation of the PI3K/AKT pathway with increased CD5L signaling in tumor endothelial cells." (PMID 37100807, 2023). "Proteins that have an anti-apoptotic effect on tumor cells or mediate adaptation to hypoxia were detected: clusterin, CD5L, HYOU1, prosaposin, and hepatocyte growth factor activator." (PMID 35659255, 2022). "Both Jchain and Cd5l were more abundant in the caerin group relative to the control, implying a more tumour-suppressive TME." (PMID 34858827, 2021). "We also identified YWHAE, PFN1, LCP1, IGHM, and CD5L as potential tumor burden markers." (PMID 40321620, 2025). "This drives a shift from the anti‐tumor CD5L+ phenotype to a pro‐tumor TREM2+ phenotype." (PMID 40552574, 2025). "Next, we examined the biological effects of CD5L upregulation in tumor endothelial cells." (PMID 37100807, 2023). "As liver plays critical roles in numerous biological processes, we speculated that CD5L dysregulation in HCC might have multiple roles during the tumor development and progression." (PMID 36494696, 2022). "To identify the materials transferred from tumor cells to macrophages, we performed enrichment analysis on scRNA‐seq data from TREM2+ macrophages and CD5L+ macrophages." (PMID 40552574, 2025). "Of these 21, we focused on 5 proteins (YWHAE, PFN1, LCP1, IGHM, CD5L) that were enriched in external CNSL cohorts, thereby supporting their utility as CNSL-enriched tumor burden biomarkers." (PMID 40321620, 2025). "And the level of CCL14 and CD5L mRNA expressions was significantly decreased in HCC tissues, revealing CCL14 and CD5L as the potential tumour-suppressor genes." (PMID 33532508, 2021). "While the potential tumor burden markers (YWHAE, PFN1, LCP1, IGHM, CD5L) are relatively abundant in CSF and have been previously implicated in various malignancies beyond CNSL, our study uniquely demonstrates their value in monitoring CNSL disease progression and treatment response." (PMID 40321620, 2025). "CD5L expression in tumor endothelial cells ranged from absent or low (upper) to high (lower) in this cohort." (PMID 37100807, 2023). "Therefore, we took a systematic approach whereby we performed mRNA profiling on tumor endothelial cells obtained from mouse models with adaptive resistance to AVA and identified CD5L as the most highly upregulated mRNA in treatment-resistant endothelial cells." (PMID 37100807, 2023). "In our previous study, CD5L expression was negatively correlated the tumor stage of HCC and its prognostic effect was not independent of the tumor stage." (PMID 36494696, 2022). "The location of CD5L was confirmed in liver cells and HCC tumor cells in HPA database." (PMID 36494696, 2022). "GRN, CD5L, ENO1, CHL1, CRISP3, VASN, and TNIK promote the invasive ability of tumor cells." (PMID 32953262, 2020). "Consistent with human CD8 GZMB+, the human-like CD8 GZMB+ clusters (Cluster0, 1) also had significantly higher Ctla4, Tox and Tox2 expression in the tumor environment injected with Macro CD5L+, while the expression of Pdcd1 (PD1) was not different between the two groups." (PMID 38245530, 2024). "The heatmaps of marker expression on the reduced dimensions showed that CD68 is the classical biomarker that is highly expressed by a large majority of macrophages; however, CD5L and MRC1 are differentially distributed with specific expression in adjacent non-malignant or tumor tissue." (PMID 36902024, 2023).
infection (14 papers, 2013 to 2025). The state of being infected such as from the introduction of a foreign agent such as serum, vaccine, antigenic substance or organism. "We confirmed that Cd5l (AIM-encoding gene) mRNA expression in the lungs of WT mice increased over time following infection, which is consistent with our previous findings." (PMID 40391046, 2025). "Overall, these data globally suggest that CD5L has a fundamental role in controlling inflammation during acute infection caused by mid-grade CLP." (PMID 38750020, 2024). "CD5L serum levels vary significantly in several pathologies, which led to consider this molecule as a diagnostic or prognostic marker in different clinical scenarios, from infection, cancer, and autoimmune diseases." (PMID 38750020, 2024). "Leukocyte recruitment to the site of infection was increased in both WT and CD5L− CLP-challenged mice, compared with sham-operated animals, but was delayed in the CD5L− mutants." (PMID 38750020, 2024). "Contingent on the type of cells rescued from programmed death, CD5L can either contribute to fighting infection and helping to resolve inflammation, or on the contrary be detrimental to disease progression." (PMID 38750020, 2024). "Previous studies have described that CD5L interacts with bacteria, thus pointing to a functional link with infection." (PMID 35330909, 2022). "In the context of infection, CD5L contributes to protecting macrophages against apoptosis induced by various microorganisms, namely Bacillus anthracis, E. coli, Salmonella typhimurium, and L. monocytogenes." (PMID 33920819, 2021). "Knowledge of the anti-apoptotic role of CD5L in infections arose from the study of nuclear receptor transcription factors LXR/RXR in infection and inflammation." (PMID 33920819, 2021). "In this review, we summarize the current knowledge of CD5L and focus on the relevance of this protein during infection- and sterile-driven inflammatory pathogenesis, highlighting its divergent roles in the modulation of inflammation." (PMID 33920819, 2021). "In vitro, CD5L macrophage expression peaked in the early phase of infection, triggering the synthesis of vitamin D-dependent antimicrobial peptides and subsequent autophagic killing of mycobacteria." (PMID 33920819, 2021). "Significant changes in serum CD5L/AIM levels were observed in both experimental groups over the course of the infection, dominated by a pronounced peak in week 3 post-infection (day 21), followed by a decrease." (PMID 29740435, 2018). "CD5L-/- peritoneal cells from mice subjected to medium-grade CLP exhibit a heightened pro-inflammatory transcriptional profile, reflecting a loss of control of the immune response to the infection." (PMID 38750020, 2024). "Moreover, a 10-fold increase in CD5L plasma levels has been described 3 weeks after murine infection with M. tuberculosis." (PMID 36982564, 2023). "Produced mainly by macrophages, CD5L is a 40-kDa glycoprotein that plays diverse roles at the intersection between lipid homeostasis and the innate immune response and thus participates in many processes, including infection, atherosclerosis and cancer." (PMID 35330909, 2022). "The heterogeneity of infectious agents in this cohort of patients may preclude the observation of systemic changes in CD5L related to infection." (PMID 35330909, 2022). "These and other roles of CD5L in infection are summarized below." (PMID 33920819, 2021). "Moreover, a variety of functions have been attributed to CD5L during the course of an infection, from the recognition and aggregation of infectious agents to the increase in the phagocytic capacity of macrophages, among other antimicrobial properties." (PMID 33920819, 2021). "There is currently no consensus on whether the specific action of CD5L upon infection is beneficial or detrimental for the host." (PMID 33920819, 2021).
bacterial infection (2 papers, 2020 to 2022). "In contrast, CD5L systemic levels were not modified in bacterial infection, although the latter is associated with substantial morbidity and mortality in these patients." (PMID 35330909, 2022). "Also related to the immune system is the CD5 molecule like (CD5L) protein, a secreted glycoprotein that participates in host response to bacterial infection and is also known to regulate lipid biosynthesis." (PMID 32671069, 2020).
infectious disease (1 paper, 2021). A disorder directly resulting from the presence and activity of a microbial, viral, or parasitic agent in humans. "Meanwhile, CD5L was located within Network 2, which was related to infectious disease, inflammatory disease, organismal injury, and abnormalities." (PMID 33808296, 2021).
CD5L also shares sentences with these, for which no sentence is quoted: Insulin resistance (3 papers); heart failure (2); acute myeloid leukemia (1); acute-on-chronic liver failure (1); adenocarcinoma (1); aneurysm (1); aortic aneurysm (1); Arrhythmia (1); atopic dermatitis (1); bacteremia (1); bacterial pneumonia (1); Chagas disease (1); cholangiocarcinoma (1); chronic hepatitis (1); congestive heart failure (1); Graves disease (1); Hepatitis (1); hyperlipidemia (1); Hypertension (1); ischemia (1); Kawasaki disease (1); kidney diseases (1); kidney stone (1); knee osteoarthritis (1); leukemia (1); liver dysfunction (1); melanoma (1); metabolic disorders (1); multiple sclerosis (1); Neurologic Disease (1).
A further 17 diseases each share a sentence with CD5L in 1 paper.